BDNF (brain derived neurotrophic factor)
Diseases named in the same sentence as BDNF in open-access papers (continued):
Sharing a sentence is not in itself a finding about the gene and the disease.
depression (continued). "In addition, stress hormones, in combination with major depressive disorder, reduce BDNF in the hippocampus and are involved in reduced neuronal survival." (PMID 30065945, 2018). "Moreover, serum BDNF levels decrease in patients with active depression or increasing psychological stress, and levels recover following treatment with antidepressant therapy." (PMID 29321655, 2018). "Exercise for depression has also been shown to increase hippocampal volume and increase serum BDNF concentrations and may be a neuroprotective mechanism that maintains cognitive ability in older age." (PMID 29559928, 2018). "Notably, data from clinical investigations and laboratory animals have provided compelling evidence that BDNF is involved in the pathogenesis of depression." (PMID 29636708, 2018). "The results are consistent with the hypothesis that the differences in the BDNF/trkB signaling and neuroplastic mechanisms are involved in the susceptibility of RLA rats and resistance of RHA rats to stress-induced depression." (PMID 30477252, 2018). "Interestingly, a decreased serum BDNF levels were observed in patients with major depressive disorders and pharmacological treatment that increases BDNF levels proved to be beneficial for depressive patients." (PMID 29593681, 2018). "BDNF is a member of the neurotrophin family of growth factors and the neurotrophic factors hypothesis of depression is nowadays widely acknowledge." (PMID 29419799, 2018). "It is well known that BDNF is strongly related to depression." (PMID 30662368, 2018). "BDNF and CREB are involved in neuronal differentiation, survival, and synaptic plasticity—which are associated with learning and memory—and in many nervous system disorders, including depression." (PMID 30046601, 2018). "First, BDNF may be a key mediator and modulator of functional synaptic plasticity, such as activity-induced long-term potentiation and long-term depression." (PMID 30524221, 2018). "Importantly, post-mortem analyses of BDNF brain content do indicate correlations between brain levels of BDNF and the rate of cognitive decline in diseases such as Alzheimer’s or Parkinson’s and in depression." (PMID 29662942, 2018). "In addition, the decreased BDNF signaling was observed in the subgenual anterior cingulate cortex in major depressive patients." (PMID 29357818, 2018). "In humans and rodents, decreasing hippocampal brain-derived neurotrophic factor (BDNF) concentrations may be involved in the onset of depression and anxiety." (PMID 30602695, 2018). "Furthermore, animal models of depression showed that antidepressant-like responses were dependent on BDNF/TrkB signaling." (PMID 30459647, 2018). "Given the overlapping symptoms and high level of comorbidity between depression and anxiety disorders, and the communities in their pathophysiology, one can assume that BDNF levels in anxiety disorders may mirror the changes found in depression." (PMID 29799860, 2018). "Therefore, compounds enhanced the level of BDNF are supposed to be helpful for the treatment of depression." (PMID 29419799, 2018). "The same neurotrophin, BDNF, showed abnormally low serum levels in major depressive disorder." (PMID 29904026, 2018). "When stratified by the type of environmental stressor, the interaction between the BDNF Val66Met polymorphism and life stress in depression became stronger for stressful life events rather than for childhood adversity." (PMID 29867348, 2018). "Subsequent findings from this study identified that the stress-induced decrease in serum and hippocampal BDNF protein and BDNF mRNA were in parallel, indicating its important role in the pathogenesis of depression and the synchronous expression level of central and peripheral BDNF alterations." (PMID 29636708, 2018). "In addition, reduced levels of BDNF have been detected in patients having, for example, Alzheimer’s disease and depression, meanwhile, elevated concentrations of BDNF have been linked to exercise." (PMID 30115826, 2018).
depression (continued). "However, MAI stimulation at SP6 significantly reduced estrogen deficit-induced depression-like behaviors and increased BDNF and NPY." (PMID 29643431, 2018). "Furthermore, since our sample was composed of low-active MDD patients, we cannot be certain if the link between BDNF, depression, and sleep quality exists in high-fit/high-active MDD patients." (PMID 29559928, 2018). "Secondly, BDNF is a hot topic in depression research worldwide." (PMID 28241064, 2017). "Despite the numerous studies reporting on the involvement of BDNF in both depression and the therapeutic effects of antidepressants, there is a relative paucity of data regarding the localization of BDNF in the hippocampus of genetic animal models of stress‐induced depression." (PMID 29075579, 2017). "Studies with antidepressants also support the neurotrophic hypothesis of depression, since chronic treatment with them increases blood BDNF levels in patients." (PMID 28134845, 2017). "Thus, it is possible that chronic SSRI treatment facilitates the resynchronization of misaligned rhythms in individuals with depression through BDNF-TrkB signaling in the SCN." (PMID 29230328, 2017). "Low levels of BDNF in cancer patients were connected with depression and poor prognosis." (PMID 29179434, 2017). "Subsequently, the GR agonist dexamethasone (Dex) was administered intrathecally to confirm whether depression-induced nociceptive alternations were mediated by spinal GRs and whether BDNF signaling was modulated by GRs in this situation." (PMID 28579944, 2017). "Indeed, a number of recent studies have reported that genes known to be implicated in depression, such as SLC6A4, NR3C1 and BDNF, are differentially methylated in peripheral blood and/or buccal cells of individuals with depression, compared to those without." (PMID 29070016, 2017). "Thus, BDNF has been found to be reduced in depression and anxiety disorders in clinical studies, while IGF-1 has been associated with the etiology of depression, particularly in learning and memory deficits, correlating with fatigue, tension and anxiety." (PMID 29108028, 2017). "There is a hypothesis that not all antidepressants generate an improvement in the serum BDNF level, like bupropion, and the improvement of this neurotrophin does not coincide with an improvement in the clinical symptoms of depression." (PMID 29299044, 2017). "A low neurotrophic activity is associated with a reduced number of cells in the prefrontal cortex, amygdala, and decreased hippocampal size, indicating that BDNF may play an important role in the development of depression." (PMID 29299044, 2017). "In the last few years, it has been hypothesized that BDNF level is related with depression and sleep." (PMID 29299044, 2017). "Thus, the purpose of this article is to trace the relationship between BDNF and insomnia in depression and what the possible result of the interaction of these factors." (PMID 29299044, 2017). "Based on these data, KXS might enhance the expressions of NGF and BDNF via regulating tPA system in stimulating synthesis of mNGF, which might account for its anti-depression effect." (PMID 28469194, 2017). "Interestingly, the reduction of BDNF and the two major TrkB isoforms is also evident in the postmortem brain of suicide victims, generally having a high incidence of previous major depression." (PMID 28134845, 2017). "The leading alternative to the monoamine hypothesis posits that depression is related to a decrease in the level of hippocampal brain-derived neurotrophic factor (BDNF) leading to decreased hippocampal neurogenesis." (PMID 29375372, 2017). "The administration of BDNF produces an antidepressant effect in two animal models of depression." (PMID 29299044, 2017). "Interestingly, the BDNF rs6265 genotype moderated the relationship between depression, self-efficacy and loneliness." (PMID 28769852, 2017).
depression (continued). "One explanation is that both NMDAR inhibition and stimulation converge on the activation of BDNF/mTOR signaling, indicating both receptor antagonists and agonists may be enlisted in treating depression." (PMID 28536503, 2017). "In addition, BDNF levels, low in proportion to the severity of mania and depression, increase with clinical improvement using antidepressants and mood stabilizers." (PMID 27905080, 2017). "There is evidence that BDNF levels influence sleep patterns in individuals with depression." (PMID 29299044, 2017). "The neurotrophic hypothesis is supported by the idea that stress and/or depression decrease expression of various neurotrophic factors (i.e. BDNF) in limbic areas and this decrease correlates with neuronal atrophy." (PMID 28646910, 2017). "BDNF knockout mice are used as an another model of depression and show marked sex differences." (PMID 29163055, 2017). "While response to ADs treatment in depression was mostly chronic, with subjects in most studies still presenting with depressive symptoms at follow-up, the effect of antidepressant drugs on the BDNF levels may take a long time." (PMID 28241064, 2017). "Together, it is likely that reduced levels of BDNF in the PFC might be implicated in the depression vulnerability in the comorbid neuropathic pain and depression." (PMID 28600519, 2017). "In conclusion, it was supposed that HJDT might be a potential Chinese medicine decoction for treating or alleviating complex symptoms of depression through BDNF-TrkB-CREB pathway." (PMID 28694833, 2017). "The brain- derived neurotrophic factor (BDNF) is a key factor in the development of depression." (PMID 30018840, 2017). "G115 promoting BDNF augmentation in ethanol-treated mice might support the survival and plasticity of neurons during stress-induced depression leading to the antidepressant effect of G115." (PMID 28837087, 2017). "The fact that participants reported relatively little anxiety and depression symptoms at baseline and improvements in these variables argues against this interpretation, as does the increase in BDNF and CAR indicative of improved psychophysiological wellness, but it must be considered." (PMID 28694775, 2017). "The BDNF met allele is known to be associated with suicidal behavior in individuals with general depression and with SI in breast cancer patients, but no such associations were found with SI in our ACS cohort." (PMID 29212281, 2017). "In addition to relate to depression, increasing amounts of data suggests that BDNF in hippocampus is a key protein involve in hippocampal neuronal plasticity and learning/memory." (PMID 28415673, 2017). "BDNF plays a prominent role in cognitive processes such as learning, memory and behavioral consolidation, and alterations in BDNF concentration can be observed in mental disorders, particularly with depression." (PMID 29108028, 2017). "The neurotrophin hypothesis of depression is based chiefly on animal study findings showing that decreased hippocampal BDNF levels are correlated with stress-induced depressive behaviors and that antidepressant administration increases the expression of BDNF." (PMID 29348904, 2017). "The reduction of serum BDNF was reported in comorbid alcohol dependence and depression patients." (PMID 28837087, 2017). "Thus, the reduction of brain BDNF has been suggested as one of the mechanisms of alcohol-induced depression." (PMID 28837087, 2017). "Vast literature affirms and typifies the eminent role of BDNF in the etiology of human depression." (PMID 29141007, 2017). "In this study, we examined whether cytokines and brain-derived neurotrophic factor (BDNF) might contribute to the individual differences in the development of neuropathic pain-induced depression." (PMID 28600519, 2017).
depression (continued). "Accordingly, by means of the same antibody used in this study, the relative levels of the BDNF mature protein in the hippocampus of the Flinders sensitive line of rats, a genetic model of depression, have been shown to be significantly lower than in their Flinders resistant controls." (PMID 29075579, 2017). "Dysregulation of hypothalamic-pituitary-adrenal (HPA) axis, monoamine and hippocampal BDNF insufficient were three cardinal hypotheses of pathogenesis of depression." (PMID 28052034, 2017). "Among neurotrophins, BDNF has been regarded as an important common mediator of depression." (PMID 28469194, 2017). "As mentioned, increased BDNF levels due to physical exercise has previously been shown to relate with hippocampal neurogenesis and likely relate to its positive effects on well-being and depression." (PMID 28694775, 2017). "They found that persons with depression at baseline, as well those with chronic late-life depression, demonstrated higher BDNF methylation levels, an effect that was influenced by the presence of three single-nucleotide polymorphisms (rs6265, rs7103411, and rs908867)." (PMID 28529805, 2017). "BDNF and CREB had been reported to involve neuronal differentiation and survival as well as the synaptic plasticity associated with learning and memory in various nervous system disorders, including depression." (PMID 28694833, 2017). "Taken together, these results indicate that ApoE4 negatively impacts BDNF–5-HT2A signaling in the female brain, which could in part underlie the ApoE4-mediated increased risk for depression." (PMID 28934977, 2017). "This suggests that BDNF could attribute to pharmacological effects of fluoxetine in treating depression." (PMID 29097744, 2017). "Therefore this study examined the effects of HJDT on the depression-like behaviors and potential mechanism involved in inflammatory reaction and BDNF-TrkB-CREB pathway." (PMID 28694833, 2017). "Previous studies demonstrated that chronic stress could lead to BDNF downregulation and BDNF plays a key role in depression recovery by promoting neuronal plasticity." (PMID 28837087, 2017). "Furthermore, an infusion of BDNF into the midbrain has an antidepressant-like influence in animal models of depression." (PMID 29348904, 2017). "In addition, activation of microglia can provoke the dysregulation of several growth factors in depression, like BDNF." (PMID 28694833, 2017). "However, since our study employed a postpartum model of depression, the effect of fluoxetine on the BDNF expression needs to be studied further in postpartum model of depression." (PMID 29317891, 2017). "This fact reinforces the hypothesis of the BDNF x depression relationship, since the use of antidepressant would improve the expression of the neurotrophic factor." (PMID 29299044, 2017). "The fact that PA modulates BDNF levels and symptoms of depression suggests that BDNF gene interactions with PA may influence depressive symptoms." (PMID 28928987, 2017). "Our result showed that CHC-mice did not affect depression-associated factors such as BDNF, serotonin, and KYN pathway." (PMID 29069807, 2017). "The reduction of BDNF is involved in the pathogenesis of mood disorders such as depression." (PMID 28591153, 2017). "Besides TNF-α, the brain-derived neurotrophic factor (BDNF) has also been considered as a depression biomarker and its plasmatic levels were evaluated." (PMID 28056040, 2017). "As it was of interest to examine whether depression would differ on levels of loneliness and self-efficacy as function of BDNF genotype, a double-moderation was performed." (PMID 28769852, 2017). "Xiaochaihutang, which is an effective TCM prescription for treating depressive disorders, contains Radix bupleuri or SSa also could upregulate the BDNF in specific brain region." (PMID 28293263, 2017).
depression (continued). "One may retort that even depression is very common among old patients with chronic diseases, and that several studies report reduced level of both BDNF and NGF serum levels in major depressive disorder which contrast our results." (PMID 28068360, 2017). "Restoration of BDNF via affiliative social interactions may not only enhance recovery, but may also help alleviate other common post-stroke disorders such as depression." (PMID 27125783, 2016). "By focusing on cognitive dimensions of depression, it is assumed that cognitive function might more closely correlate with biological markers (e.g., BDNF, inflammatory marker) than a global syndrome of depression consisting of a variety of symptoms clusters." (PMID 27616997, 2016). "Studies that focus on depression and BDNF may provide insights that might facilitate the improvement of interventions for SCLC." (PMID 27852063, 2016). "In fact, mental stress-induced hypermethylation of the brain-derived neurotrophic factor (BDNF) gene was demonstrated in the hippocampal region in a mouse model of depression, and abnormal DNA methylation of BDNF in peripheral blood is subsequently shown in the individuals with major depression." (PMID 28933395, 2016). "Moreover, this phenolic compound has been shown to reverse chronic stress-induced impairment of hippocampal neurogenesis and increase expression of brain-derived neurotrophic factor (BDNF) in an animal model of depression." (PMID 26903869, 2016). "Although the precise mechanism is under investigation, abnormalities in BDNF-TrkB signaling may substantially contribute to the development of depression in PD." (PMID 27525025, 2016). "Wang J indicated that Geniposide can alleviate depression-like behavior, which may partially be ascribed to the upregulation of BDNF expression in the brain." (PMID 27852063, 2016). "The possible role of dysfunctional BDNF activity in the prefrontal cortex in depression may be mediated by the BDNF-neurotrophin receptor tyrosine kinase 2 signaling pathway, which contributes to the molecular vulnerability in depression." (PMID 26876488, 2016). "Several molecules relevant to pathophysiology of depression, including BDNF, ERK1/2, Akt and GSK3β, could be modulated by agomelatine." (PMID 27877109, 2016). "Thus, social defeat stress causes decreased BDNF-TrkB signaling in the hippocampus and PFC, but an increased BDNF-TrkB signaling in the NAc, resulting in depression-like behavior in mice." (PMID 27991542, 2016). "Previous studies indicated that modifications in the expression of BDNF in the hippocampus may correlate with depression, and our previous findings demonstrated that HMF enhanced the synthesis of BDNF in the hippocampus of the ischemic brain." (PMID 27120588, 2016). "Yoga may have a positive effect on depression and other psychological co-morbidities, with maintenance of serum BDNF and serotonin levels." (PMID 27231715, 2016). "Last, we asked whether the behavioral effects of EET reflect BDNF levels in the hippocampus and frontal cortex, two regions where dysfunction is related to depression." (PMID 27648918, 2016). "BDNF has already been shown to enhance mental abilities at the same time as acting against anxiety and depression in mice, and might act in similar way in humans." (PMID 27253067, 2016). "Using our unique mouse model of depression that lacks promoter IV-driven BDNF expression (KIV mice), here we tested our hypotheses by determining the antidepressive and BDNF effects of EET across ages: ED, young adult and old adult." (PMID 27648918, 2016). "Furthermore, BDNF has been shown to be involved in synaptic plasticity as well as in long-term potentiation and depression." (PMID 28066217, 2016). "Deletion of BDNF also produces chronic pain and depressive-like behavior in mice, and stimulators of BDNF synthesis have been shown to have an analgesic effect and reduce depression-like behavior in rats with chronic pain." (PMID 27918444, 2016).